TNF (tumor necrosis factor)
Diseases named in the same sentence as TNF in open-access papers (continued):
Sharing a sentence is not in itself a finding about the gene and the disease.
Hepatitis (continued). "Inflammatory cytokines such as IFNγ, IL-4 and TNFα that are produced by activated NKT cells are essential mediators for induction of hepatitis." (PMID 22347449, 2012). "Although the cells and cytokines that mediate liver damage in IL-10−/− mice have yet to be clearly identified, it has been established that overproduction of IFN-γ and TNF-α can promote the development of severe hepatitis during acute MCMV infection." (PMID 22880122, 2012). "It appears that IL-4 can regulate TNFα production in ConA-induced hepatitis, as exogenous IL-4 can boost TNFα levels." (PMID 22347449, 2012). "Our experiments revealed that the induction of hepatitis by CD4+ T cells depended at least in part on TNFα." (PMID 21966366, 2011). "Although TACE inhibitors are efficient in protecting against lipopolysaccharide/d-(+)-galactosamine-induced lethal hepatitis by inhibition of TNF-α release, inhibition of TACE by BB-94 was deemed irrelevant in their model; however, data was not shown." (PMID 20593020, 2010). "The anti-TNF agent employed inhibited concavalin A-induced hepatitis, demonstrating that the reagent is biologically active." (PMID 17352828, 2007). "Simultaneously, stigmasterol can also inhibit the activation of the nuclear factor-κB (NF-κB) pathway, reduce the secretion of inflammatory factors such as tumor necrosis factor-α (TNF-α), interleukin-6 (IL-6), and interleukin-1β (IL-1β), and alleviate liver inflammation." (PMID 40363681, 2025). "Currently, inflammatory markers such as CRP, IL-1β, and TNF-α are widely used to evaluate hepatitis, but these markers may lack specificity." (PMID 39996800, 2025). "Accumulation of liver lipids and activation of macrophages as well as the accumulation of liver lipids influences the release of the proinflammatory factors leukotriene-6, tumor necrosis factor-alpha, and interleukin-1, which result in liver inflammation, steatosis, and cell injury." (PMID 38887554, 2024). "In this study, INH-induced pro-inflammatory marker gene expressions such as TNF-α, TGF-β, and NF-κB are responsible for liver inflammation and fibrosis and this could be the possible cause for the onset of INH-induced liver inflammation and hepatotoxicity." (PMID 38313882, 2024). "Infliximab, a mouse–human chimeric monoclonal antibody anti-TNFα, should not be given to patients with hepatitis because infliximab carries a risk of hepatotoxicity." (PMID 38398187, 2024). "The results showed that IL-1β, IL-6, and TNF-α levels were observably increased in the M group, and QJ treatment significantly downregulated this change, which further confirmed that QJ inhibited CCl4-induced liver inflammation." (PMID 38606180, 2024). "Notably, both MSCs and LPS-stimulated MSCs attenuated the production of pro-inflammatory cytokines, such as IL-6 and TNF-α, leading to a reduction in liver inflammation." (PMID 38116551, 2023). "It appears that an increase in IL-6, TNF-α, and s-ICAM-1 in the course of EBV infection may indicate the risk of hepatitis with concomitant biliary pole damage." (PMID 37834802, 2023). "Some hepatic non-immune cells, including endothelial cells and HSC, also have TLRs on their surface that recognize bacterial-specific structural components and subsequently release substantial cytokines such as IL-1, IL-6, and TNF-α, further promoting fibrosis and liver inflammation." (PMID 37872967, 2023). "Liver inflammation, on the other hand, was assessed through the levels of IL-6, TNFα, and IL-1β." (PMID 37296638, 2023). "Increased concentrations of IL-6, TNF-α, and s-ICAM-1 may indicate the risk of hepatitis with concomitant biliary pole damage during EBV infection." (PMID 37834802, 2023). "Our experimental findings showed that in the phase of inflammation regression, HRP inhibited NF-κB by upregulating PKA activated by cAMP and inhibited TNF-α and IL-1β, which resulted in liver inflammation regression and restoration of damaged CYP2D6 and liver function." (PMID 37833431, 2023).
Hepatitis (continued). "For instance, studies showed that baicalin could reduce the expressions levels of TNF-α and NF-κB in liver tissue and the production of TNF-α, IL-1β, and IL-6 in plasma, thus reducing the degree of liver inflammation." (PMID 37298268, 2023). "In this patient, ATIL coexisted with anti-TNF-induced hepatitis." (PMID 37175894, 2023). "For HIV and hepatitis C and E, enhanced TNF-a levels play a role in the detrimental effects." (PMID 36768699, 2023). "Sequentially, CBZ exposure induced liver inflammation in the treated rats; this was evidenced by a significant trigger of NF-κB generation, which can induce the pro-inflammatory biomarkers (TNF-α, and IL-6) to increase in comparison with their levels in the control group." (PMID 37375275, 2023). "Interestingly, neutralization of TNF resulted in elevated levels of serum transaminases which was probably due to T cell–mediated hepatitis." (PMID 35122118, 2022). "TNF-α plays an important role in the clearance of hepatitis B virus from infected hepatocytes, therefore TNFi may lead to hepatitis reactivation or disease worsening." (PMID 35203438, 2022). "To investigate the anti-inflammatory property of curcuminoids, we determined the expression of common inflammatory markers, such as the toll-like receptors (TLRs) on the surface of innate immune cells, hepatitis cytokines tumor necrosis factor (TNF)-α, and interleukin (IL)-6 in MCD-diet mice." (PMID 35723408, 2022). "Notably, in ConA-hepatitis, TNF mediates liver injury in its soluble and transmembrane-bound precursor form that depends on activation of both TNF receptors." (PMID 35122118, 2022). "Interestingly, TRAPS mutant (T79M and G87V) mice had reduced mortality rates after the administration of lipopolysaccharide (LPS) and D-galactosamine, which induce TNFα-dependent lethal hepatitis." (PMID 35936010, 2022). "Moreover, PLEKHO2-deficient mice display greatly increased hepatotoxicity and ultimately lethality after TNFα-induced hepatitis." (PMID 34272357, 2021). "Systemic inflammatory response, including TNF, IL-8, IL-6, and IL-2, contributes to the transition from stable chronic liver disease to HBV-ACLF, which is associated with morbidity and mortality of hepatitis." (PMID 33868273, 2021). "KEGG analysis showed that intersect genes involved in toll-like receptor (TLR) signaling, cellular senescence, hepatitis B, chemokine signaling pathway, IL−17 signaling pathway, viral protein interaction with cytokine and cytokine receptor, and TNF signaling pathway." (PMID 33623529, 2021). "In addition, we noted that both compounds ameliorated the symptoms of ConA-induced hepatitis in mice and decreased the activities of transaminases and the concentrations of TNF-α in the serum at 8 h following the administration of ConA." (PMID 33919375, 2021). "Pretreatment of mice with anti-mouse TNF-α antiserum can protect them from ConA-induced hepatitis." (PMID 34654474, 2021). "Moreover, JGXZ treatment attenuated the inflammatory response in NAFLD model rats, manifesting as mild lobular liver inflammation and reduced expression of proinflammatory cytokines (IL-6, IL-1β, and TNF-α) in the serum and liver." (PMID 33824675, 2021). "KEGG enrichment of core targets contained some pathways related to CLI, such as hepatitis B, tumor necrosis factor (TNF) signaling pathway, apoptosis, hepatitis C, interleukin-17 (IL-17) signaling pathway, and hypoxia-inducible factor (HIF)-1 signaling pathway." (PMID 33747110, 2021). "The activation of the NF-κB signaling pathway leads to the phosphorylation of p65 in the nucleus, which then triggers a series of physiological or pathological effects (such as the production of inflammatory cytokines, including TNF-α, IL-1β and IL-6), which eventually leads to hepatitis." (PMID 34945677, 2021). "Furthermore, the successful inhibition of TNF-mediated hepatitis proposes LRH-1 inhibition as a novel therapeutic approach in the treatment of acute inflammatory disorder." (PMID 32111818, 2020).
Hepatitis (continued). "TNF-α was increased by the interaction of lipoplex with BSA in hepatitis mice." (PMID 32290201, 2020). "Furthermore, quantitative RT-PCR indicated a decreased expression of hepatitis-related genes, such as tumor necrosis factor-α, IL-6, and IL-1β in OVX rats after BCE treatment." (PMID 32466275, 2020). "Significantly, higher levels of TNFα, IL-6, and IL-8 were observed in cases of severe hepatitis." (PMID 32124729, 2020). "Consequently, curcumin administration induces these PTM regulations of the NF-κB pathway, presumably reducing the production of IL-6 and TNF- α and eventually suppressing hepatitis." (PMID 31717261, 2019). "In the present work, the antinflammatory capability of Baishouwu extract mainly resulted in decreased levels of MyD88, TRAF6, NF-κB, IL-6 and TNF-α via the reduction of TLR4 expression in hepatitis, cirrhosis, and hepatocarcinoma stages of the HCC models induced by DEN." (PMID 31068809, 2019). "Con A induces overproduction of TNF-α which amplify the inflammatory response in hepatitis." (PMID 29643811, 2018). "This may mimic events in vivo in which an inflammatory hepatic cytokine microenvironment, found in hepatitis or cancer, dominated by IL‐1, IL‐2, IL‐6, IL‐12, IL‐15, IL‐18, IFNα, IFNγ, and TNFα/β 38, 39, may lead to the expansion of CD49a+ NK cells." (PMID 28952190, 2018). "In vivo intervention with recombinant human interleukin-1 receptor antagonist (rhIL-1Ra) strongly suppressed ConA-induced hepatitis by decreasing tumor necrosis factor-alpha (TNF-α) and interleukin-17 (IL-17) secretion, and inflammatory cell infiltration into livers." (PMID 29692782, 2018). "Abnormalities in liver functions tests, including transient and self-limiting hypertransaminasemia, cholestatic disease and hepatitis can develop during treatment with anti-TNF-α and, in some cases, they could be severe and life threatening." (PMID 30060508, 2018). "In addition, more CD4+ T cells than macrophages expressed these cytokines, suggesting that CD4+ T cells are the main source of TNFα and IFNγ during ConA hepatitis." (PMID 30462657, 2018). "Thus, it is assumed that TNFα and IL-6 produced by KCs play a significant role in the pathogenesis of the hepatitis." (PMID 28804705, 2017). "OI developed a highly severe acute disease with higher parasitemia, TNF serum levels, hepatitis and mortality rates when compared to GI, suggesting that the inoculum site is a key factor in Chagas disease progression, possibly modulating local immune mechanisms that impacts in the systemic immunity." (PMID 28379959, 2017). "With reference to liver cytokine milieu, IL-10 levels showed an inverse relation with fibrosis severity (significant fibrosis p = 0.0398, advanced fibrosis p = 0.0291) whereas TNF-α and TGF-β were associated with hepatitis severity (p = 0.0409, p = 0.0321; respectively)." (PMID 29038590, 2017). "TNF-α and TGF-β were associated with hepatitis severity (p = 0.0409, p = 0.0321)." (PMID 29038590, 2017). "As in prior studies, we found that MTX use without folic acid was positively associated with the risk of ALT elevation; however, no study has compared the risk of MTX-related hepatitis in anti-TNF users with differing HBV infection status." (PMID 29089055, 2017). "Thus, comparing to GI mice, we observed that OI mice presented elevated infection rate and parasitemia, higher TNF serum levels, more severe hepatitis and milder carditis." (PMID 28379959, 2017). "The production of TNF and FasL indicated that they are the pivotal effectors in this hepatitis." (PMID 27708340, 2016). "TNF-α and FasL-induced mouse hepatitis models exhibit activation of effector caspase-3." (PMID 27431384, 2016). "However, hepatitis was also detected despite a widespread activation of the NF-κB signaling pathway in hepatocytes of TNF-α-treated Ripk1LPC-KO mice." (PMID 27831558, 2016).
Hepatitis (continued). "We took advantage of two different deficient mouse lines, the RIPK1 kinase dead knock-in mice (Ripk1K45A) and the conditional knockout mice lacking RIPK1 only in liver parenchymal cells (Ripk1LPC-KO), to characterize the role of RIPK1 and TNF-α in hepatitis induced by concanavalin A (ConA)." (PMID 27831558, 2016). "Since TNF is also an essential mediator in several forms of acute hepatitis, we evaluated the therapeutic potential of miR-511 in the concanavalin (ConA) model of acute, TNF-mediated hepatitis." (PMID 25995337, 2015). "Interestingly, transient in vivo delivery of miR-511 down-regulated TNFR1 in livers of mice and protected them not only against TNF, but also against endotoxic shock (in a TNFR1-dependent way) and in a model of TNF-mediated lethal hepatitis (induced by ConA)." (PMID 25995337, 2015). "Thus, treatment with NAC attenuated the release of ConA-induced hepatitis-associated cytokines, such as IL-2, IL-6, IFN-γ, and TNF-α." (PMID 25821351, 2015). "Additionally, IL-2, IL-6, IFN-γ, and TNF-α expression peaked at 12 h, indicating that these cytokines were most robustly expressed during the early phase of ConA-induced hepatitis." (PMID 25821351, 2015). "TNF-α released by activated hepatic macrophages is one of the very important factors that damage hepatocytes, which are highly sensitive to cell-extrinsic stimulation in Fas-mediated hepatitis." (PMID 24392145, 2014). "In addition, IL-2, IL-6, IL-1β and TNF-α were maximally expressed at 6h, indicating these four cytokines mainly expressed in the early phase of Con A-induced hepatitis." (PMID 24498418, 2014). "IFN-γ and TNF-α are pivotal functional cytokines for viral control and pathogenesis of hepatitis." (PMID 24520324, 2014). "Furthermore, CD11b+ Kupffer cells play an important role in the acute phase of CCl4-induced hepatitis as a result of their production of TNF and FasL, which occurs in an NKT cell-independent manner." (PMID 24667392, 2014). "Furthermore, previous studies have reported that fumigaclavine C acts against Con A-induced hepatitis in mice by inhibiting T cell proliferation, adhesion and TNF-α production." (PMID 24351905, 2013). "Moreover, the mice pretreated with endogenous HNE inhibitor α1-AT were unable to secrete TNF-α in response to d-galactosamine with lipopolysaccharide (LPS) and were therefore fully protected against d-galactosamine with LPS-induced hepatitis." (PMID 24376583, 2013). "Through transcriptional arrest of hepatocytes, GalN with endotoxin or TNFα had been reported to induce acute apoptotic hepatitis in mice, whereas GalN pre-treatment markedly diminished the increased APAP hepatitis in Il15−/− mice versus a minor advantage in WT controls." (PMID 23028657, 2012). "In the study of peripheral blood mononuclear cells (PBMCs) collected from acute Q fever patients, the production of TNF, IL-6, IL-12, and IL-10 was higher than in control subjects, and TNF and IL-10 levels were higher in patients with hepatitis than in those with isolated fever." (PMID 20594295, 2010). "Since Ninj1 KO in myeloid cells did not attenuate hepatitis caused by LPS/D‐gal, we investigated whether loss of Ninj1 influences TNF‐α‐induced hepatocyte death." (PMID 36071453, 2022). "In addition, IL-17, which is produced by pro-inflammatory T helper 17 (Th17) cells, can promote liver inflammation and fibrosis by facilitating the production of IL-6, IL-1, and TNF-α by inflammatory cells and activating hepatic stellate cells to produce collagen type I." (PMID 36425072, 2022). "Also, TNF‐α secreted by macrophage is a main player in LPS/D‐gal‐induced hepatitis model." (PMID 36071453, 2022). "The results presented in this paper imply that a selective diminution of PDE7 activity caused anti-inflammatory and hepatoprotective effects in the ConA-induced hepatitis model and the observed outcomes may be attributed to the suppression of TNF-α and production of IFN-γ." (PMID 33919375, 2021).
Hepatitis (continued). "Experimental studies in animals have demonstrated that liver injury in ConA-induced hepatitis is associated with activated CD4+T cells, macrophages, and natural killer T (NKT) cells that cause hepatocyte injury by producing lots of pro-inflammatory cytokines, particularly IFN-γ and TNF-α." (PMID 32742600, 2020). "Here TNF-α, which emerged from a response to a viral pathogen associated molecular pattern (PAMP) recognized by the TLR3, was most probably produced by Kupffer cells as their previous chemical depletion prevented the development of hepatitis in poly I:C challenged Ripk1LPC-KO mice." (PMID 30622241, 2019). "The most significantly altered pathways were hepatitis B, Epstein–Barr virus infection, human T-cell lymphotropic virus type 1 (HTLV-1) infection, Kaposi’s sarcoma-associated herpesvirus, nuclear factor-kappa B (NFKB) signaling pathway, hepatitis C, and tumor necrosis factor (TNF) signaling pathway." (PMID 31849586, 2019). "Since cytokines in the serum had been reported to be associated with liver inflammation and dysfunction, patients with liver dysfunction had significantly higher level of IL-2R, IL-6, IL-10, and TNF-α in the serum, when compared with those without liver dysfunction (p < 0.001)." (PMID 29109622, 2017). "In addition, TNF-α and TGF-β were associated with higher HAI values, which may represent their role in hepatitis regulation." (PMID 29038590, 2017). "However, in the animal model of ConA-induced hepatitis, TNF-α could participate in autophagy through the interactions between Beclin-1 and Bcl-2 or between FADD and Atg5." (PMID 25761053, 2015). "Therefore, increased circulating levels of TNFα released as a consequence of hepatitis-induced stimulation of the immune system may diminish tumor viability." (PMID 23426187, 2013). "Its immunosuppressive activity against concanavalin A-induced hepatitis in mice by the mechanisms of inhibiting T cell proliferation, adhesion and TNF-α production has been reported previously, suggesting that fumigaclavine C may have a characteristic to inhibit the T-cell mediated immune response." (PMID 24351905, 2013). "We have recently reported that another variant of memTNF (deletion 1–9 and substitution Lys to Glu in position 11, memTNFΔ1–9,K11E) in KI mice was not pathogenic for liver inflammation but only soluble TNF was causing hepatitis in LPS/BCG and LPS/D-GalN-induced liver damage." (PMID 22666310, 2012). "Proinflammatory cytokines released from activated T cells and macrophages, including TNF-α, IFN-γ, IL-6, and CXCL1, are critical in ConA-induced hepatitis." (PMID 40092485, 2025). "The serum IL-1β, IL-6, TNF-α, TBIL, DBIL, ALT, AST and ALP levels decreased with rats treated with PZW where reduced liver inflammation halted its fibrosis and improved overall hepatic health." (PMID 41293246, 2025). "Since inflammatory cytokines, such as tumor necrosis factor-α (TNF-α) derived from Kupffer cells, play an important role in the progression of CCl4-induced hepatitis, the effect of Man-MSA-mIFNα2 on TNF-α production was investigated using ELISA." (PMID 38399475, 2024). "In hepatitis C, HCV induces and maintains the production of CHI3L1 in liver parenchymal cells by synergistically inducing the TNF-α and ROS-MAPKs pathways through the sustained activation of NF-κB." (PMID 38962736, 2024). "It appears to either directly or indirectly suppress the expression of pro-inflammatory cytokines such as TNF, IL6, and IL1B, thus alleviating liver inflammation." (PMID 38755697, 2024). "It was shown that IL-6, TNF-α, and s-ICAM-1 concentrations were the highest in patients with hepatitis and biliary pole damage." (PMID 37834802, 2023). "Interestingly TNF had the highest relevance scores of 75.06, 77.71, 69.39, 95.44, 51.13 for acetaminophen, isoniazid, D-galactosamine, lipopolysaccharide, and rifampicin-induced hepatitis, respectively, and for thioacetamide, IL6 had the highest relevance score of 55.21." (PMID 37446321, 2023).